NEURL4 (neuralized E3 ubiquitin protein ligase 4)
Description:
Promotes CCP110 ubiquitination and proteasome-dependent degradation. By counteracting accumulation of CP110, maintains normal centriolar homeostasis and preventing formation of ectopic microtubular organizing centers.
Synonyms: KIAA1787
Tractability: Small molecule: it has a high-quality binding pocket. PROTAC: UniProt records ubiquitination sites on it; ubiquitination databases record sites on it; its protein half-life has been measured.
Gene: Protein-coding gene on chromosome 17 (7,315,628 to 7,329,393, reverse strand). Ensembl gene ENSG00000215041.
Subcellular location: Cytoplasm, cytoskeleton, microtubule organizing center, centrosome, centriole
Gene Ontology:
Molecular function: DNA binding; NAD+-dinitrogen-reductase ADP-D-ribosyltransferase activity; protein binding; ubiquitin protein ligase activity
Biological process: mitochondrial DNA repair
Cellular component: mitochondrial matrix; mitochondrion; centriole
Genetic constraint (gnomAD): Loss-of-function variants: 44 observed, 148.13 expected, observed/expected ratio (o/e) 0.3, 90% interval 0.23 to 0.38. The upper end of that interval is the gene's LOEUF score, 0.38, which puts it in group 1 of 6, group 1 being the genes least tolerant of losing a copy. Missense variants: 1,753 observed, 2,156.9 expected, observed/expected ratio (o/e) 0.81, 90% interval 0.78 to 0.85. Synonymous variants: 835 observed, 868.98 expected, observed/expected ratio (o/e) 0.96, 90% interval 0.91 to 1.02.
Homologues: Orthologues: chimpanzee NEURL4 (99% identical), macaque NEURL4 (99% identical), pig NEURL4 (97% identical), guinea pig NEURL4 (96% identical), dog NEURL4 (96% identical), mouse Neurl4 (96% identical), rat Neurl4 (96% identical), zebrafish neurl4 (69% identical), tropical clawed frog neurl4 (65% identical), Drosophila melanogaster Neurl4 (39% identical). Paralogues in human: NEURL1 (9% identical), NEURL1B (8% identical), NEURL3 (5% identical).
Diseases named in the same sentence as NEURL4 in open-access papers:
NEURL4 is named in the same sentence as 5 diseases in open-access papers, as found by Europe PMC text mining. Sharing a sentence is not in itself a finding about the gene and the disease. The quoted sentences say what the papers report.
prostate carcinoma (2 papers, 2017 to 2019). A carcinoma that arises from epithelial cells of the prostate gland. "According to this model, NEURL4 should also function as a tumor suppressor and in agreement with this, analysis of cancer genomics datasets from the cBioPortal shows a high frequency in NEURL4 deletions in prostate cancer." (PMID 31275856, 2019).
autism (1 paper, 2023). Persistent deficits in social interaction and communication and interaction as well as a markedly restricted repertoire of activity and interest as well as repetitive patterns of behavior. "HERC2 interacts with the autism-linked ubiquitin ligase RNF8/UBC13 and the scaffold protein NEURL4, taking part in a novel cytoplasmic ubiquitin-signalling network that suppresses synapse formation in the brain." (PMID 37307281, 2023).
lung carcinoma (1 paper, 2023). "Consistent with this idea, RNF8 localizes to the cytoplasm where it interacts with HERC2 and NEURL4 in neurons, IKKα/β, as well as Akt in lung cancer." (PMID 37468549, 2023).
cancer (3 papers, 2017 to 2020). A tumor composed of atypical neoplastic, often pleomorphic cells that invade other tissues. "Taking all these data into account, we identified the following candidates as potential causes of CA in human cancer: gain of function of CEP19, CEP72, CTNNB1, PTK2, NDRG1, SPATC1, TBCCD1; and loss of function of CEP76, MCPH1, NEURL4, NPM1." (PMID 32681070, 2020). "Consequently, deletions of NEURL4 gene could enhance tumorigenesis in some types of cancer." (PMID 28977907, 2017).
NEURL4 also shares sentences with these, for which no sentence is quoted: tumor (2 papers).